SOX9 (SRY-box transcription factor 9)
Diseases named in the same sentence as SOX9 in open-access papers (continued):
Sharing a sentence is not in itself a finding about the gene and the disease.
acanthoma (1 paper, 2020). A benign skin neoplasm composed of epithelial cells. "Sox9-positive cells were mainly present among the basaloid neoplastic cells of infundibular keratinizing acanthoma." (PMID 32397255, 2020).
acinar cell carcinoma (1 paper, 2017). "Human PC of ductal lineage expresses Sox-9 but pancreatic neuroendocrine tumors, acinar cell carcinomas and solid pseudopapillary neoplasms rarely express Sox-9." (PMID 28475592, 2017).
acute lung injury (1 paper, 2021). A condition of lung damage that is characterized by bilateral pulmonary infiltrates (pulmonary edema) rich in neutrophils, and in the absence of clinical heart failure. "Such protective effects of SOX-9 have previously been observed in an acute lung injury (ALI) model, where SOX-9 was activated in the post-ALI phase and assumed to promote recovery of the damaged lungs." (PMID 33693012, 2021).
Adrenal insufficiency (1 paper, 2013). Insufficient production of steroid hormones (primarily cortisol) by the adrenal glands. "Complete sex reversal in 46,XY males without adrenal insufficiency can also occur in conditions such as Leydig cell hypoplasia or due to mutations in SRY, DHH, SOX9, DMRT1, WNT1, or ATRX." (PMID 23748066, 2013).
age (1 paper, 2022). A temporal measurement of the time period elapsed since an identifiable point in the life cycle of an organism. "SOX9, COL2 and rounded-cell morphology were previously seen in ligaments of spontaneous OA mouse models and in ligaments of age-related human OA, indicating similar pathology post-trauma and in age-related OA." (PMID 35637500, 2022).
aging (1 paper, 2022). A developmental process that is a deterioration and loss of function over time. "The results showed that claudin 2 was closely related to SOX9, and both claudin 2 and SOX9 were closely related to the process of skin aging." (PMID 35965621, 2022).
ankylosis (1 paper, 2014). Fixation and immobility of a joint. "Previous reports show that tissue-specific inactivation of Shox2 in the cranial neural crest cells leads to TMJ dysplasia and ankylosis, accompanied by significant down-regulation of Sox9, Runx2 and Ihh." (PMID 25062348, 2014).
Anonychia (1 paper, 2020). Aplasia of the nail. "Fortunately, our three patients provide strong evidence that 17q24.3 duplications related to regulatory elements of SOX9 as well as KCNJ2 coding region are a genetic cause of brachydactyly‐anonychia." (PMID 32583964, 2020).
aortic aneurysm (1 paper, 2022). A ruptured aneurysm located in the wall of the proximal portion of the descending aorta proceeding from the arch of the aorta. "By contrast, reduced SOX9 levels associated with fibulin-5 downregulation have been found in human aortic aneurysms, highlighting the different role of this factor depending on the pathology." (PMID 36499730, 2022).
aortic stenosis (1 paper, 2012). Aortic valve stenosis is a aortic valve disease caused by the incomplete opening of the aortic valve. "Since reduced levels of Sox9 have been shown to be causally related to valve ossification, the observed differences are consistent with a model in which affected valve tissues in Alk2 mutants with aortic stenosis and insufficiency display pro-osteogenic changes." (PMID 22536403, 2012).
aortic valve disease (1 paper, 2022). "In addition, we analyzed the protein localization of Sox9 and Aggrecan (key proteins implicated in the pathogenesis of aortic valve disease), as well as Wnt7a and Opg (which showed altered expression in RNASeq) using immunohistochemistry." (PMID 36005436, 2022). "Among these, a mouse model of premature aging (Klotho−/−) and heterozygote Npr2+/− and tissue-specific Sox9 mutants represents models in which genetic modification alone results in aortic valve disease." (PMID 36005436, 2022).
Atherosclerotic lesion (1 paper, 2022). A lesion associated with atherosclerosis, a multifactorial and multipart progressive disease manifested by the focal development within the arterial wall of lesions, that ranges from the development of a fatty streak, plaque progression, and plaque disruption. "Genes upregulated by SOX9 expression in HUVECs overlapped with genes upregulated in fibroblasts versus endothelial cells in atherosclerotic lesions, while genes downregulated by SOX9 expression in HUVECs were enriched in endothelial cells versus fibroblasts in atherosclerotic lesions." (PMID 35904801, 2022).
autism (1 paper, 2015). Persistent deficits in social interaction and communication and interaction as well as a markedly restricted repertoire of activity and interest as well as repetitive patterns of behavior. "SOX9 is a transcription factor essential for skeletal development, but it is also involved in the development of the male phenotype, thus contributing to the increased risk of autism in males." (PMID 24621061, 2015).
autism spectrum disorder (1 paper, 2016). A spectrum of developmental disorders that includes autism, and Asperger syndrome. "Among the many genes in region are ZNF219, which encodes a transcriptional partner of Sox9 essential for chondrogenesis in mice, and CHD8, mutations in which are associated with autism spectrum disorder in conjunction with macrocephaly and distinct facial features including a broad nose." (PMID 27560520, 2016).
Autoimmunity (1 paper, 2025). The occurrence of an immune reaction against the organism's own cells or tissues. "HSP60, though often discussed in autoimmunity, supports chondrocyte mitochondrial integrity and stabilizes SOX9; its deficiency in damaged cartilage aligns with impaired anabolic capacity and heightened inflammatory tone." (PMID 41472751, 2025).
B-cell acute lymphoblastic leukaemia (1 paper, 2011). "The growth arrest-specific 7, Gas7, is regulated by Sox9 and the ERK1/2 MAP kinase and is involved in chondrogenesis, and has been reported to form a MLL/GAS7 fusion protein in a pediatric case of B-cell acute lymphoblastic leukaemia." (PMID 21492432, 2011).
basosquamous carcinoma (1 paper, 2020). A basal cell carcinoma which displays squamous differentiation. "In the stained SCC samples, Sox9-positive cells were mainly present in the neoplastic cells showing basal cell morphology, in infiltrating areas, and with a high level of expression (25%–50% of positive cells) in the specific SCC histotype known as basosquamous carcinoma." (PMID 32397255, 2020).
brachydactyly (1 paper, 2020). A disease characterized by the presence of brachydactyly, including syndromic and non-syndromic forms. "We firstly identified a new subtype of brachydactyly in a large Chinese family carrying the similar duplication involving in regulatory region of SOX9 (17q24.3), which is important for the future gene diagnosis." (PMID 32583964, 2020).
B‐cell lymphoma (1 paper, 2025). "However, the relationship between BCL2 and SOX9 in haematological malignancies, especially B‐cell lymphoma, is poorly understood." (PMID 40356256, 2025).
cardiac arrest (1 paper, 2025). Cessation of breathing and/or cardiac function. "Pro-EMT markers phospho-Smad1/5, Sox9, and Twist1 were downregulated in the AVC endocardium after cardiac arrest." (PMID 39932433, 2025).
cerebral infarction (1 paper, 2020). An ischemic condition of the brain, producing a persistent focal neurological deficit in the area of distribution of the cerebral arteries. "The results displayed that SOX9 silencing inhibited cerebral infarction area and cell apoptosis in MCAO-operated rats, but this inhibitory effect was abolished by overexpression of IKKα." (PMID 33791290, 2020).
cerebral tumour (1 paper, 2017). "Our results point to the conclusion that Sox2 and Sox9, seem to play essential roles not only in the specific formation of aCP, but also in processes involving the cerebral tumour environment, which needs to be illuminated in the future." (PMID 29158570, 2017).
cervical (1 paper, 2015). "Furthermore, SOX9 expression was positively correlated with nuclear p21 expression in 23 cervical specimens from patients with CC (r = 0.5655, P < 0.05), which supports the notion that SOX9 positively regulates p21 expression in cervical carcinogenesis." (PMID 26036262, 2015).
CHARGE syndrome (1 paper, 2019). CHARGE syndrome is a multiple congenital anomaly syndrome characterized by the variable combination of multiple anomalies, mainly Coloboma; Choanal atresia/stenosis; Cranial nerve dysfunction; Characteristic ear anomalies (known as the major 4 C's). "Several genes were reported only in syndromic cases; CHD7 (CHARGE syndrome), CR1 (van der Woude syndrome), EFNB1 (craniofrontonasal syndrome), KISS1R (Kallmann syndrome), MID1 (Opitz G/BBB syndrome), REN (van der Woude syndrome), and SOX9 (Pierre-Robin syndrome)." (PMID 31122291, 2019).
Chlamydial infection (1 paper, 2024). "Furthermore, Chlamydial infection notably induced the expression of early chondrogenesis gene Sox9." (PMID 39467689, 2024).
choriocarcinoma (1 paper, 2021). An aggressive malignant tumor arising from trophoblastic cells. "Both tumors have choriocarcinoma components, so it can be speculated that SOX9 is also expressed in choriocarcinoma; however, confirmation needs further study." (PMID 34881182, 2021).
chronic lung disease (1 paper, 2018). According to the definitions of the American and British Thoracic Societies, including pulmonary functional tests, X-rays, and CT scans for items such as fibrosis, bronchiectasis, bullae, emphysema, nodular or lymphomatous abnormalities. "Most importantly, we showed that SOX9+ BCs cultured under GMP guidelines can be applied clinically in order to reconstitute human lung for devastating chronic lung disease treatment." (PMID 29344809, 2018). "Most importantly, for the first time we explored the clinical feasibility of autologous SOX9+ BC transplantation to treat two patients with chronic lung diseases." (PMID 29344809, 2018). "In conclusion, our study clearly shows the capability of SOX9+ BCs to regenerate human lung, proves the concept of chronic lung disease treatment by SOX9+ BC transplantation and provides exciting translational opportunities in near future." (PMID 29344809, 2018).
chronic pancreatitis (1 paper, 2023). A chronic inflammatory process causing damage and fibrosis of the pancreatic parenchyma. "Interestingly, in the immunohistochemical analysis of Sox9 expression using tissue microarrays, both chronic pancreatitis tissue and low-grade PanINs were found to be generally Sox9-positive, while in higher-grade pancreatic lesions, the Sox9 expression was more heterogeneous." (PMID 37894295, 2023).
congenital hypothyroidism (1 paper, 2013). A thyroid hormone deficiency present from birth. "Among them, the reported signals at SOX9, ABO, SASH1, GLIS3 and MIR1179 will need to be confirmed in other studies; but one of them - GLIS3- is a prime candidate, because it is involved in congenital hypothyroidism." (PMID 23408906, 2013).
cryptorchidism (1 paper, 2025). The failure of one or both testes of a male fetus to descend from the abdomen into the scrotum during the late part of pregnancy. "In the same way, in vivo KCTD13-null mice exhibited reduced nuclear AR levels, decreased expression of SOX9, smaller testis, cryptorchidism, micropenis, and subfertility." (PMID 41595460, 2025).
cystic neoplasm (1 paper, 2021). A benign or malignant neoplasm that contains a single or multiple cystic spaces. "This study revealed a Jag1-controlled phenotypic switch between PDAC and largely benign cystic neoplasms, which appeared to be associated with differential expression of Lkb1 and Sox9 in pancreatic ductal cells." (PMID 33268505, 2021). "With the same Sox9-CreER, concurrent Lkb1 deletion and Kras activation in the ductal epithelium resulted in IPMN in adult mice, whereas deletion of Jag1 combined with KrasG12D expression in the ductal epithelium failed to induce cystic neoplasm." (PMID 33268505, 2021).
dementia (1 paper, 2023). Loss of intellectual abilities interfering with an individual's social and occupational functions. "Overall, no studies have looked in the role of SOX9 in dementia, however, SOX9 expression was found to be upregulated in diseases such as multiple strokes." (PMID 37065298, 2023).
dental pulp inflammation (1 paper, 2026). "A previous study showed that SOX9, as a downstream target of TNF-α, plays an important role in dental pulp inflammation and immune responses." (PMID 41207115, 2026).
embryonal carcinoma (1 paper, 2011). A non-seminomatous malignant germ cell tumor characterized by the presence of large germ cells with abundant cytoplasm resembling epithelial cells, geographic necrosis, high mitotic activity, and pseudoglandular and pseudopapillary structures formation. "We demonstrate that endogenous SOX9 is upregulated in the human embryonal carcinoma cell line NT2/D1 over-expressing SRY, a model of presumptive Sertoli cells." (PMID 21412441, 2011). "To test whether human SRY can activate SOX9 transcription we evaluated the human embryonal carcinoma cell line, NT2/D1, as a model of presumptive Sertoli cells." (PMID 21412441, 2011).
embryonic testis carcinoma (1 paper, 2018). "While it is difficult to know the exact sequence of events during activation of human SOX9 in vivo, analysis of H3K27ac enhancer ChIP indicated that these three enhancer regions are active in an embryonic testis carcinoma cell line, NT2-D1." (PMID 30552336, 2018).
emphysema (1 paper, 2022). "Importantly, administration of FGF10 rescued glycocalyx impairment and emphysema in a murine model of COPD, probably through a FGFR1/ERK/SOX9/HS6ST1 loop in endothelial cells." (PMID 36183124, 2022).
endolymphatic hydrops (1 paper, 2025). An accumulation of endolymph in the inner ear (labyrinth) leading to buildup of pressure and distortion of intralabyrinthine structures, such as cochlea and semicircular canals. "In the postnatal stria vascularis, there is impaired normal interaction of SOX9 and SOX10, repressing the expression of the water channel Aquaporin 3, thereby contributing to endolymphatic hydrops." (PMID 40109362, 2025).
endometrioid tumor (1 paper, 2025). A benign, borderline, or malignant epithelial tumor of the female reproductive system characterized by the presence of glands and/or cysts lined by neoplastic cells that resemble endometrial cells. "In organoid models from endometrioid tumors, cells expressing ALDH1 or SOX9 alone and cells not expressing any stemness markers (low) were less prevalent while cells expressing only CD15 were significantly more prevalent." (PMID 39888143, 2025).
eosinophilia (1 paper, 2025). "Coinciding with these pathological alterations, SOX9 loss dramatically altered hepatic immune cell responses, including more pronounced eosinophilia, a reduction in CD4+ T cell proportions and heightened frequency of Ly6lo monocytes." (PMID 40489560, 2025). "Infected SOX9–deficient mice also displayed exaggerated Type 2 inflammation, including pronounced eosinophilia." (PMID 40489560, 2025). "As expected, irrespective of SOX9 depletion status, schistosome infections were accompanied by significant eosinophilia, but with SOX9 -/- mice showing a strong tendency towards higher eosinophil proportions than WT infected controls." (PMID 40489560, 2025). "In particular, SOX9 deficiency led to the dispersed arrangement of F4/80+ cells and altered CD4+ T cell phenotypes, with pronounced eosinophilia and monocyte recruitment; potentially suggesting signals from the fibrotic ECM help tether immune cells to the granuloma or modulate their function." (PMID 40489560, 2025).
Ewing sarcoma (1 paper, 2019). A small round cell tumor that lacks morphologic, immunohistochemical, and electron microscopic evidence of neuroectodermal differentiation. "The positive staining for Sox9 along with negative staining for FLI-1 aids in distinguishing MC from Ewing sarcoma." (PMID 30909775, 2019).
extraskeletal osteosarcoma (1 paper, 2021). "The tumor cells exhibited heterogeneous protein expression, including a positive expression of vimentin, cytokeratin, RANKL, CRLR, SOX9, and collagen 2, and was diagnosed as extraskeletal osteosarcoma." (PMID 34941834, 2021).
fibrosarcoma (1 paper, 2020). A malignant mesenchymal fibroblastic neoplasm affecting the soft tissue and bone. "Real-time PCR analysis showed that silencing SAPCD2 decreased expression levels of multiple downstream genes of the Hippo pathway, including CTGF, CYR61, SOX9, HOXA1, RPL13A, and PPIA in fibrosarcoma cells." (PMID 33384953, 2020).
fragile X syndrome (1 paper, 2021). A genetic syndrome caused by mutations in the FMR1 gene which is responsible for the expression of the fragile X mental retardation 1 protein. "Significant down-regulation of SOX9 expression has been revealed in neural progenitors derived from Fragile X Syndrome ESCs while downregulation of SOX10 expression is detected in brains of patients with schizophrenia." (PMID 33867936, 2021). "Interestingly, down-regulation of SOX9 expression has been detected in neural progenitors derived from Fragile X Syndrome human ESCs." (PMID 33867936, 2021).
gallbladder cancer (1 paper, 2024). "This study explores epigenetic mechanisms underlying oncogenesis of gallbladder cancer (GBC), revealing SOX9 and TCF7L2 can form a core regulatory circuitry (CRC) to drive oncogenic SE reprogramming and subsequent transcriptional activation of critical malignant genes." (PMID 39492805, 2024).
gallstones (1 paper, 2020). Solid crystalline precipitates in the biliary tract, usually formed in the gallbladder, resulting in the condition of cholelithiasis. "For pathological analysis of human gallbladders, we first examined the SOX17/SOX9 expression profiles in seven non-BA [six congenital biliary dilation (CBD) cases, one gallstone (GS) case] and eight control [one pancreatoblastoma (PB) case, seven hepatoblastoma (HB) cases] gallbladders." (PMID 31996362, 2020).
gastric disease (1 paper, 2021). "Similar to FABP1, the two-stage expression pattern of CDX2 and SOX9 during the initiation and development of GC was also reported previously, suggesting that these molecules might play different roles in different stages of gastric disease progression." (PMID 34957220, 2021).
goblet cell adenocarcinomas (1 paper, 2023). "In addition, frameshift mutations of SOX9 are reported in a few appendiceal goblet cell adenocarcinomas." (PMID 37509254, 2023).
Granuloma (1 paper, 2025). A compact, organized collection of mature mononuclear phagocytes, which may be but is not necessarily accompanied by accessory features such as necrosis. "In stark contrast, SOX9-/- granulomas lost their coordinated halo of collagen, instead presenting a more disorganised and diffuse arrangement of ECM components, and the staining for these matrix components was less intense, reminiscent of reduced fibrosis." (PMID 40489560, 2025).
head and neck cancer (1 paper, 2014). A primary or metastatic malignant neoplasm affecting the head and neck. "miR145 could target the SOX9/ADAM17 axis and inhibit tumor-initiating cells and IL-6-mediated paracrine effects in head and neck cancer." (PMID 24941171, 2014).
HELLP syndrome (1 paper, 2023). A life-threatening condition that can potentially complicate pregnancy. "The aim of this study was to investigate SOX9 and Hif-1α expression of in placentas of women with HELLP syndrome by immunohistochemical methods." (PMID 37878989, 2023). "In this study, we investigated the immunohistochemical staining of SRY-box transcription factor 9 (SOX9) and Hif-1α expression in placentas of pregnant woman with hemolysis, elevated liver enzymes and low platelets (HELLP) syndrome." (PMID 37878989, 2023).
hip fracture (1 paper, 2021). Traumatic or pathological injury to the hip in which the continuity of either the femoral head, femoral neck, intertrochanteric or subtrochanteric regions is broken. "The SOX9 locus has previously been found to associate with increased risk of hip fracture." (PMID 33285254, 2021).